KRAS (KRas proto-oncogene, GTPase)
Diseases named in the same sentence as KRAS in open-access papers (continued):
Sharing a sentence is not in itself a finding about the gene and the disease.
breast cancer (continued). "The three cases with significant treatment-by-biomarker interaction in an RCT were cetuximab/KRAS and panitumumab/KRAS, both for metastatic colorectal cancer; and anastrozole/hormonal receptor for adjuvant treatment of early breast cancer." (PMID 28761069, 2017). "Althoughstudies of some cancers, such as lung and breast cancer, have demonstrated thatLet-7 miRNAs directly repress KRAS mRNA,KRAS has not been found to be a Let-7 target in studies ofCRC." (PMID 28250048, 2017). "For example, we observed that the oncogenic KRAS expressing breast cancer cell line MDA MB 231 showed much higher levels of S100A10 compared to MCF7 breast cancer cells (that do not express oncogenic RAS)." (PMID 27351226, 2016). "Let-7 family miRNAs have been well-documented to target HRAS to regulate self-renewal and tumorigenicity and to sensitize KRAS mutant breast cancer to paclitaxel and gemcitabine." (PMID 27462780, 2016). "A human breast carcinoma cell line that expresses an activated KRAS protein has been shown to have high glycolytic flux, low TCA cycle activity, and increased usage of glutamine for anabolic synthesis." (PMID 27924922, 2016). "At last, we provide evidence that miR-200c can inhibit the proliferation and clone formation of breast cancer in vitro by targeting KRAS." (PMID 26392416, 2015). "Repression of KRAS by miR-200c suppressed the proliferation and survival of breast cancer cells in vitro and in vivo." (PMID 26392416, 2015). "As expected, knockdown of CAT significantly recovered the ROS generation and enhanced migration and invasion, colony formation in low dose irradiation treated KRAS overexpressed breast cancer cells." (PMID 26515758, 2015). "It is noteworthy that as a well-known oncogene, KRAS is mostly activated and overexpressed in more than 35–40% malignancies, including breast cancer." (PMID 26515758, 2015). "AKT1, KRAS and PIK3CA mutations and PTEN loss all exist in women with breast cancer in the mainland China." (PMID 25816324, 2015). "This is exemplified by the analysis of the breast cancer dataset, from which the well-known but rarely mutated cancer genes CDKN1B (7 mutations out of 772 samples), KRAS (6 mutations) and MEN1 (5 mutations) were identified." (PMID 25903787, 2015). "Our findings provide clues regarding the role of miR-200c as a tumor suppressor in breast cancer through the inhibition of KRAS translation both in vitro and in vivo." (PMID 26392416, 2015). "Then, we detected the expression of miR-200c and KRAS in 41 pairs of breast cancer tissues (BC) and their matched normal adjacent tissues (CTR)." (PMID 26392416, 2015). "Abnormal activation of PI3K/AKT/mTOR (PAM) pathway, caused by PIK3CA mutation, KRAS mutation, PTEN loss, or AKT1 mutation, is one of the most frequent signaling abnormalities in breast carcinoma." (PMID 25816324, 2015). "We show that KRAS is a predicted target of miR-200c and that the protein expression of KRAS inversely correlates with the miR-200c expression in a panel of human breast cancer cell lines." (PMID 24368337, 2014). "The miR-200c-positive breast cancer cell line BT-474 was treated with doxorubicin for three rounds, which resulted in reduced miR-200c and elevated K-ras protein levels suggesting a miR-200c-dependent regulation of KRAS." (PMID 24368337, 2014). "Interestingly, the sensitivity to SREBP depletion was not restricted to RPE cells but could also be demonstrated in a panel of breast cancer cell lines in which the PI3-kinase pathway is activated by loss of function of PTEN or activating mutations in PIK3CA or KRAS." (PMID 24280005, 2013). "As it is well documented that the tumour-suppressor let-7 family regulates KRAS in pancreatic, lung, colon and breast cancers, we concentrated on miR-126 as a novel KRAS targeting miRNA in PDAC." (PMID 22384141, 2012).
breast cancer (continued). "Here, we have demonstrated that KRAS inhibition through direct regulation by miR-30c leads to reduced proliferation in breast cancer cells." (PMID 22701724, 2012). "Although mutations in KRAS are infrequent in breast tumors, activation of KRAS pathway in breast cancer have been frequently found." (PMID 22701724, 2012). "There is also evidence that breast cancer cell lines with a basal phenotype have a higher frequency of mutations in BRAF, KRAS, and HRAS than luminal breast cancer cell lines." (PMID 20604919, 2010). "For example, analysis of chromatin accessibility in KPC, KC, and WT mice identified ATF3 binding sites as one of the highest enriched motifs in open chromatin regions after KRASG12D was expressed and ATF3 affects KRAS signaling in breast cancer models by regulating KRAS expression through miRNAs." (PMID 41198649, 2025). "In summary, these results imply that this SNV in breast cancer may be fundamental to the formation of a new KRAS G4 structure." (PMID 40725120, 2025). "In addition to the structural alterations caused by SNVs, we also observed the formation of a novel G4 motif in the promoter region of KRAS in breast cancer." (PMID 40725120, 2025). "In breast cancer patients overall, KRAS is not the most common genetic mutation, but it is present in around 30% of TNBCs." (PMID 40362524, 2025). "Parallel to that, here, we identified differences in intracellular Ca2+ response after ATP-activated P2Y2 receptor signaling in metastatic breast cancer cells with oncogenic KRas mutations compared to non-malignant breast epithelial cells." (PMID 40362524, 2025). "The PCAIs constitute a novel group of anticancer agents designed to treat cancers driven primarily by KRAS and related proteins or those that rely on them as resistance genotypes, such as the drug-resistant forms of breast cancer that are the subject of the present study." (PMID 40736275, 2025). "Furthermore, the disruption of mutant hyperactive growth factor receptor signaling at the level of KRAS in the MAP kinase pathway offers yet more options for breast cancer management." (PMID 38540084, 2024). "In our study, we observed that this miRNA is overexpressed in PC (logFC 0.76) and that it modulates KRAS within the genomic locus of SNV rs9266, which has been previously reported to be associated with breast cancer in the Mexican population and a sample of the Chinese population." (PMID 39057123, 2024). "Also, a study on breast cancer reported that KRAS promotes mesenchymal phenotypes of basal-type breast cancer cells through SLUG expression among EMT transcription factors." (PMID 38522060, 2024). "Furthermore, both breast cancer cell lines exhibited significant reductions in the levels of KRAS, RHOA, RAC1, and CDC42 proteins of 49, 40, 50, and 48%, respectively in MDA-MB-468 cells." (PMID 36961909, 2023). "KRAS is a key oncogene in cancer, inhibition of KRAS signaling inhibits EMT in breast cancer." (PMID 37280589, 2023). "We investigated this hypothesis in breast cancer models characterized by different ER+ HER2+ receptors profile and mutations of PI3KCA/PTEN or KRAS/B-RAF." (PMID 35761360, 2022). "Moreover, miR-1 has been shown to suppress breast cancer development by downregulating KRAS and MALAT1 transcription, which emphasizes the potential role of miR-1 as a tumor-suppressive miRNA and MALAT1 as an oncogenic lncRNA via the regulation of KRAS." (PMID 34489556, 2022).
breast cancer (continued). "As a first approach to examining the biological significance of elevated YB-1 expression on the in vivo tumorigenic properties of human breast cancer cells with altered KRAS or AKT expression, we focused on determining the effect of reducing YB-1 protein levels in MDA-MB-231 cells." (PMID 34294889, 2022). "In a series of 6464 metastatic breast cancer samples, genomic alterations of KRAS, including mutations and amplifications but no fusions, were described in about 2.3% of the patients." (PMID 36358725, 2022). "In the present study, three arene Ru(II) complexes coordinated with different substituent phenanthroimidazole derivatives were synthesized under microwave irradiation and studied for their ability to stabilize KRAS G-quadruplex DNA and inhibit the proliferation of breast cancer cells." (PMID 35630522, 2022). "Moreover, the proliferation and metastasis of multiple tumors, including breast cancer, can be inhibited by different small molecules regulating the expression of KRAS." (PMID 35630522, 2022). "Hence, the development of a KRAS G-quadruplex DNA binding agent is a new strategy to inhibit the growth of breast cancer cells." (PMID 35630522, 2022). "For example, a recent report demonstrated that treatment of ER+ breast cancer and KRAS-mutant NSCLC cells with eIF4A inhibitor could inhibit cell cycle feedback response and drug-resistance to CDK4/6 inhibitor treatment." (PMID 33414445, 2021). "For quite some time, the role of KRAS in breast cancer has not been a point of focus since KRAS mutations are infrequent in this cancer type." (PMID 33801965, 2021). "To assess the full developmental potential of mammary cancer cells and their ability to diversify into heterogeneous lineages, we developed a mammary tumor model where the continuous expression of oncogenic KRAS is untethered from a mammary epithelial-specific promoter (left)." (PMID 34145248, 2021). "KRAS holds a prominent cooperative role with hPRLr in breast cancer pathogenesis." (PMID 33772010, 2021). "The collective observations on the EF1-tTA-mediated, transgenic expression model, and mammary tumors that express oncogenic KRAS from the endogenous locus suggested that RAS signaling is a determinant for the genesis of basal-like and claudin-low molecular subtypes." (PMID 34145248, 2021). "This culture model system, therefore, provided a unique opportunity to study whether the maintenance of the mesenchymal characteristics of claudin-low mammary cancer cells is dependent on the persistent expression of oncogenic KRAS." (PMID 34145248, 2021). "Once activated in the luminal epithelium, the expression of exogenous or endogenous mutant KRAS occurs in a differentiation-independent manner in both mammary cancer models, which is a prerequisite to uncover the full extent of cellular plasticity that is mediated by the oncogenic driver." (PMID 34675248, 2021). "Gene-set enrichment analysis has shown that important pathways are upregulated in response to SK1 knockdown in prostate and breast cancer cells, like KRAS, IL2/STAT5, EMT and TNF/NFκB, indicating that switching off one pathway is insufficient to completely block cancer cell growth." (PMID 34043703, 2021). "Finally, this proof-of-principle study provides evidence that the JAK1 tyrosine kinase plays a central role in the constitutive activation of STAT3 in KRAS-transformed mammary cancer cells." (PMID 34675248, 2021). "In addition to upstream effectors influencing RAS activity, certain regulators of KRAS, such as R-RasGTPases, mediate the interaction between estrogen and insulin signaling in breast cancer cells." (PMID 33801965, 2021). "To date, no successful therapies have been found to target KRAS mutations in ER+ CDK4/6 inhibitor-resistant breast cancer." (PMID 34830174, 2021).
breast cancer (continued). "The collective results from the histopathological and molecular characterization suggest that expression of oncogenic KRAS under the control of the MMTV-tTA is sufficient to initiate the development of poorly differentiated mammary carcinomas that have the propensity to metastasize." (PMID 34145248, 2021). "We hypothesized that miR-143 suppresses breast cancer progression by targeting KRAS and its effector molecules." (PMID 32370060, 2020). "In addition, we also analyzed HERVs that were associated, by localization, with breast cancer development genes (BRCA1, CCND1, ATM, NBS1/NBN, RAD50, KRAS, PI3K/PIK3CA)." (PMID 33194615, 2020). "Furthermore, the florescent labeling analysis results of breast cancer progression revealed that miR-30c binds 3'UTP of KRAS transcripts and silences the expression of KRAS mRNA and protein, which further inhibit the metastasis of breast cancer cells." (PMID 32201529, 2020). "Moreover, SNVs within KRAS in the primary tumors of the METABRIC data set, although rare (0.6% of patients), were significantly associated with poor survival in human breast cancer." (PMID 32463822, 2020). "Similarly, IL-8 has been reported to enhance migration and thus metastasis of breast carcinoma cells MDA-MB231, which also carry a KRAS G13D mutation." (PMID 32314963, 2020). "Considering also that MMTV–PAK4 overexpression may have facilitated KRAS-driven mammary tumors, and that oncogenic RAS-signaling in untransformed cells activates OIS3, we tested the hypothesis that PAK4 may overcome oncogenic RAS-induced senescence." (PMID 31399573, 2019). "Of the non-breast cancer patients, 13 out of 52 had KRAS G12 hotspot alterations." (PMID 31546879, 2019). "However, BRAF and KRAS mutations are rare in breast cancer with BRAF and KRAS mutated in 0.45% and 0.54% of The Cancer Genome Atlas (TCGA) breast cancer genomes respectively." (PMID 30658422, 2019). "Furthermore, a large percentage of breast cancers were found to have measurable levels of mutations in critical genes of the MAP kinase pathway (i.e., KRAS, HRAS, and BRAF)." (PMID 30813596, 2019). "Although KRAS mutations are not commonly found in breast cancer, the pathway seems to be hyperactive due to mutation in NF1, epigenetic silencing of DUSP4 or other alternatives that lead to non-canonical MAPK activation." (PMID 30777101, 2019). "Finally, the use of OncoScantm has allowed us to detected mutations in five genes that have not been shown to be mutated in TCGA subset of Her-2 overexpressing breast cancer: CTNNB1, HRAS, KRAS, NF2 and SMARCB1." (PMID 28247034, 2017). "Importantly, we confirmed the involvement of BCL-XL in mammosphere formation in second-generation assays in KRASV12 cells as well as in mammosphere formation in the KRAS wild type human breast cancer cell line MDA-MB-468." (PMID 29066722, 2017). "It was reported that breast cancer rarely possessed ERK pathway kinases mutations, BRAF (2%), KRAS (5%), and HRAS (1%) mutations occur at even lower frequency in TNBC, only a few of studies recognized breast cancer as a good candidate of ERK pathway targeting therapy." (PMID 29296238, 2017).
breast cancer (continued). "Some contradictories are discovered to be mainly relative to the order of KRAS and PIK3CA alteration, that is, whether PIK3CA alteration as a part of RAS pathway is the late event after KRAS alteration or PIK3CA the late event in breast cancer." (PMID 27190992, 2016). "Total PCBs associated with AREG, CYP19A1, ESR2, FOS, KRAS and STC2 genes; PCB 126 associated with AREG, CYP19A1, and STC2 genes and PCB 15 associated with CYP19A1, EGFR, ESR2, FOS, and IGF1 genes overlapped with 17β-estradiol, breast cancer, and endometriosis." (PMID 26512648, 2015). "Of 12 patients (colorectal, n = 6; appendiceal cancer, n = 2; NSCLC, n = 2; duodenal, n = 1; breast cancer, n = 1) who had KRAS G12 or G13 mutations in the tumor tissue did not have these mutations in their cfDNA." (PMID 25980577, 2015). "We predicted and verified KRAS as a target of miR-200c in breast cancer." (PMID 26392416, 2015). "Moreover, we also reported that KRAS promoted mesenchymal features in basal type breast cancer cells." (PMID 26515758, 2015). "The human breast cancer cell line MCF-7 were used as wild-type for both KRAS and BRAF genes." (PMID 23536897, 2013). "However wild-type KRAS is significantly activated in breast cancers that over-express EGFR and ErbB2." (PMID 22701724, 2012). "The lack of association between the KRAS variant and sporadic postmenopausal breast cancer is in line with the previous findings reported by Paranjape and colleagues." (PMID 22436609, 2012). "In addition, we provide evidence that KRAS is a target of miR-30c, and that this miRNA suppresses breast cancer cell growth potentially through inhibition of KRAS signaling." (PMID 22701724, 2012). "The association of the KRAS-variant with ovarian cancer was most significant for uninformative women from HBOC families, and the association with breast cancer was significant for premenopausal women with triple negative breast cancer, also often indicative of an HBOC family." (PMID 22662244, 2012). "Since the KRAS variant was reported to be enriched in ovarian cancer patients from HBOC families, the study by Hollestelle and colleagues further investigated the frequency of the KRAS variant in breast cancer families." (PMID 22436609, 2012). "Assessment of the mutation status of KRAS might also be of potential relevance in other EGFR-overexpressing tumors, such as those occurring in breast cancer." (PMID 20385028, 2010). "In addition, we examined whether SNV-driven G4 signals in the promoter region of KRAS could be detected in breast cancer or other cellular contexts to confirm cancer-type specific G4 formation." (PMID 40725120, 2025). "Interestingly, while TELB haplotype has been linked to better response to trastuzumab in HER2+ breast cancer, we found no such association in KRAS-WT CRC patients treated with cetuximab." (PMID 40869384, 2025). "It is difficult to know whether the KRAS mutation or the lack of it is responsible for the observed opposing effects of PCAIs on AKT phosphorylation between the two breast cancer cell lines." (PMID 38540084, 2024). "Considering that the KRAS oncogene plays a key role in the pathogenesis, progression, and growth of breast cancer cells, the interaction of complex 1 with KRAS G-quadruplex DNA may serve as a promising target for anti-breast cancer." (PMID 35630522, 2022).